ENSG00000251012 (novel chromosome 3 open reading frame 30 (C3orf30) and uroplakin 1B (UPK1B))
Gene: Protein-coding gene on chromosome 3 (119,147,375 to 119,187,807, forward strand). Ensembl gene ENSG00000251012.
Genetic constraint (gnomAD): Loss-of-function variants: 3 observed, 7.21 expected, observed/expected ratio (o/e) 0.42, 90% interval 0.19 to 1.08. That is too few expected variants to judge how well the gene tolerates losing a copy. Missense variants: 99 observed, 100.88 expected, observed/expected ratio (o/e) 0.98, 90% interval 0.83 to 1.16. Synonymous variants: 40 observed, 36.97 expected, observed/expected ratio (o/e) 1.08, 90% interval 0.84 to 1.41.